UCA1 (urothelial cancer associated 1)
Diseases named in the same sentence as UCA1 in open-access papers (continued):
Sharing a sentence is not in itself a finding about the gene and the disease.
coronary heart disease (1 paper, 2022). "Long noncoding RNA urothelial cancer‐associated 1 (lnc‐UCA1) targets microRNA‐26a (miR‐26a) and microRNA‐195 (miR‐195) to participate in coronary heart disease (CHD) progression via regulation of vascular smooth muscle cell and microvascular endothelial cell viability and mobility." (PMID 34850451, 2022).
endothelial dysfunction (1 paper, 2022). In vascular diseases, endothelial dysfunction is a systemic pathological state of the endothelium (the inner lining of blood vessels) and can be broadly defined as an imbalance between vasodilating and vasoconstricting substances produced by (or acting on) the endothelium. "In endothelial cells, UCA1 formed a ternary complex with USP14 and PFN1, prolonged the half-life of the PFN1 protein, and subsequently activated the RhoA/ROCK pathway to produce excess ROS and induce endothelial dysfunction." (PMID 36160709, 2022).
gynecologic cancers (1 paper, 2025). "The dual behavior of UCA1 across comparisons supports its context-specific role, which has also been suggested in other gynecologic and non-gynecologic cancers." (PMID 41226033, 2025).
head and neck squamous cell carcinoma (1 paper, 2018). A squamous cell carcinoma that arises from any of the following anatomic sites: lip and oral cavity, nasal cavity, paranasal sinuses, pharynx, larynx, and salivary glands. "Although research on lncRNAs for head and neck squamous cell carcinoma is limited, a recent study has reported few differentially expressed lncRNAs such as HOTAIR, NEAT1, UCA1, and MALAT1, in oral cancers." (PMID 30002503, 2018).
hemangioma (1 paper, 2021). A benign vascular lesion characterized by the formation of capillary-sized or cavernous vascular channels. "UCA1 knockdown can also regulate signal transduction of mTOR via miR-200c and miR-195, and inhibit the proliferation and invasion of hemangioma cells and microvascular endothelial cells." (PMID 33777227, 2021). "Previous studies have reported that UCA1 regulates the Wnt/β-catenin signaling pathway via miR-200c and miR-185-5p, and affects the proliferation and EMT in hemangioma and melanoma cells, respectively." (PMID 33777227, 2021). "In addition, UCA1 knockdown regulates AMPK signal transduction via miR-200c and suppresses the proliferation, migration and invasion of hemangioma cells." (PMID 33777227, 2021).
laryngeal neoplasm (1 paper, 2022). A benign or malignant neoplasm involving the larynx. "ROC curve analysis suggested that serum UCA1 may potentially serve as a diagnostic marker for laryngeal neoplasm (area under the curve was 0.8905, with a 95% confidence interval of 0.8408 to 0.9402, p < 0.0001)." (PMID 35406495, 2022).
liver cirrhosis (1 paper, 2024). "Interestingly, liver cirrhosis displayed a distinct lncRNA profile: UCA1 upregulation and downregulation of LINC00152 and GAS5 (p = 0.02, 0.001, and 0.001, respectively)." (PMID 39609501, 2024).
lung neoplasm (1 paper, 2022). A benign or malignant, primary or metastatic neoplasm involving the lungs. "We predict that TUG1, PTENP1, and UCA1 may be the biomarkers of lung neoplasms, NSCLC and LUAD, respectively." (PMID 35938010, 2022).
Miscarriage (1 paper, 2019). A pregnancy that ends at a stage in which the fetus is incapable of surviving on its own, defined as the spontaneous loss of a fetus before the 22th week of pregnancy. "Here, we sought to unravel the roles of UCA1 in the occurrence of the recurrent miscarriage (RM) disorders." (PMID 31572567, 2019).
osteoarthritis (1 paper, 2017). A noninflammatory degenerative joint disease occurring chiefly in older persons, characterized by degeneration of the articular cartilage, hypertrophy of bone at the margins and changes in the synovial membrane. "However, little is known about the role of UCA1 in the osteoarthritis." (PMID 29207643, 2017).
ovarian serous cystadenocarcinoma (1 paper, 2025). A malignant serous cystic epithelial neoplasm arising from the ovary. "Scatter plots show the correlations between FAM171A2 mRNA expression and six lncRNAs (BACE1-AS, GAS5, HOTAIR, HOXA10-AS, PVT1, and UCA1) in ovarian serous cystadenocarcinoma samples (n = 379) from the ENCORI database." (PMID 41303609, 2025).
ovarian tumors (1 paper, 2022). "Expression levels of DSCAM1-AS1, CCAT1, MALAT1, MAFG-DT, and UCA1 were increased in ovarian tumors but were not markedly different from the normal tissue group." (PMID 35453574, 2022).
pancreatic disease (1 paper, 2014). "Therefore, our results suggested that UCA1 might be associated with pancreatic disease." (PMID 24498199, 2014).
polyp (1 paper, 2025). A usually exophytic mass attached to the underlying tissue by a broad base or a thin stalk. "The combination of older age and elevated UCA1 in EP patients aligns with epidemiological data linking perimenopause to polyp development via unopposed estrogen exposure." (PMID 41226033, 2025).
prostate adenocarcinoma (1 paper, 2022). "However, UCA1 expression was significantly lower in kidney chromophobe (KICH), kidney renal clear cell carcinoma (KIRC), liver hepatocellular carcinoma (LIHC), and prostate adenocarcinoma (PRAD) compared with adjacent normal tissues." (PMID 35794986, 2022).
pulmonary fibrosis (1 paper, 2021). Chronic progressive interstitial lung disorder characterized by the replacement of the lung tissue by connective tissue, leading to progressive dyspnea, respiratory failure, or right heart failure. "FOSL2, also known as FRA-2, is an activator protein 1 (AP-1) transcription factor and was reported to promote pulmonary fibrosis, cardiac fibrosis, and skin fibrosis, and be regulated by lncRNA UCA1 in ceRNA networks during tumorigenesis." (PMID 34715879, 2021).
respiratory system cancer (1 paper, 2019). "However, the significance of UCA1 in LNM in respiratory system cancers and RNU6B/GUSB reference control group should incorporate more studies to validate this result, and so does in urinary system prognosis and non-Asian people prognosis." (PMID 30918102, 2019).
serous adenocarcinoma (1 paper, 2024). An adenocarcinoma that is characterized by the presence of papillary patterns and cellular budding. "UCA1 was overexpressed in high-grade serous adenocarcinoma tissues and significantly associated with prognosis, while its locus was marked by a tumor-specific super-enhancer, regulating its expression." (PMID 38534790, 2024). "Interestingly, one study demonstrated UCA1 as a super-enhancer-associated gene, particularly sensitive to treatment with the BET inhibitor (+)-JQ1 in the high-grade serous adenocarcinoma CaOV3 and UWB1.289 cells." (PMID 38534790, 2024). "Two studies illustrated the ability of UCA1 to induce PTX resistance in SKOV3 and high-grade serous adenocarcinoma HeyA8 cells by regulating the expression of two miRNAs and their target genes: miR-129/ABCB1 and miR-654-5p/SIK, respectively." (PMID 38534790, 2024). "Moreover, SKOV3 and clear cell adenocarcinoma RMG-1 cells exhibited higher UCA1 and enhanced green fluorescent protein (EGFP) levels, and more cytopathic effects and OVV replication than serous cystadenocarcinoma SHIN3 and high-grade serous adenocarcinoma ES-2 and OVCAR3 cells." (PMID 38534790, 2024).
serous cystadenocarcinoma (1 paper, 2024). A malignant serous cystic neoplasm usually involving the ovary or the pancreas. "The last study additionally featured an in vivo experiment, showcasing the suppression of cancer development following the inhibition of UCA1 in the serous cystadenocarcinoma OVCA249 mouse xenograft models." (PMID 38534790, 2024). "The enhanced capacity of UCA1 to promote PTX resistance was further confirmed by observing higher UCA1 levels in serous cystadenocarcinoma PTX-resistant KFTX and KFTXlow cells, compared to the PTX-sensitive KFlow cells." (PMID 38534790, 2024). "Conversely, silencing the short isoform of UCA1 elevated miR-27a-5p and BIM expressions, leading to enhanced sensitization of established DDP-resistant serous cystadenocarcinoma OAW42 cells to DDP." (PMID 38534790, 2024).
temporal lobe epilepsy (1 paper, 2021). A localization-related (focal) form of epilepsy characterized by recurrent seizures that arise from foci within the temporal lobe, most commonly from its mesial aspect. "LncRNA urothelial cancer-associated 1 (UCA1) expression is down-regulated in the hippocampus of temporal lobe epilepsy rats." (PMID 34675776, 2021).
ulcerative colitis (1 paper, 2022). An inflammatory bowel disease involving the mucosal surface of the large intestine and rectum. "LncRNA UCA1 expedites the progression of ulcerative colitis via mediating the miR-331-3p/BRD4 axis." (PMID 35259053, 2022).
urothelial dysplasia (1 paper, 2015). A morphologic finding indicating the presence of dysplastic changes in the transitional cell epithelium of the urinary tract. "This hypothesis is supported by the detection of UCA1 in all seven cases of CIS and, additionally, in two cases of urothelial dysplasia (data not shown)." (PMID 26191476, 2015).
vulvar cancer (1 paper, 2024). "Although there were some opposing results, UCA1 was predominantly found to be upregulated in most of the breast, endometrial, ovarian, cervical, and vulvar cancer cells, tissue samples, and mouse xenograft models." (PMID 38534790, 2024).
tumor (297 papers, 2013 to 2025). "For instance, in BC cell line 5637, lncRNA urothelial cancer-associated 1 (UCA1) is secreted during hypoxia condition and aids tumor promotion via epithelial-mesenchymal transition (EMT)." (PMID 39925739, 2025). "Urothelial carcinoma-associated 1 (UCA1) is an oncogene that promotes tumor cell proliferation, migration, and invasion while inhibiting tumor cell apoptosis." (PMID 39871377, 2025). "Risk score = 0.268 ∗ P4HA1 - 0.168 ∗ CCDC148 + 0.094 ∗ UCA1 + 0.054 ∗ TMPRSS11E + 0.31 ∗ Tumor Stage." (PMID 41080752, 2025). "The SKOV3 mouse xenografts additionally exposed the reduced DDP sensitivity and increased tumor progression caused by UCA1 overexpression." (PMID 38534790, 2024). "In the SiHa, Me180, and C33a cells, which are also representative of SCC of the cervix, UCA1 was found to be overexpressed and implicated in promoting tumor development." (PMID 38534790, 2024). "The downregulation of miR-299-3p and subsequent tumor development caused by UCA1 overexpression were obvious in the CC tissues, as well." (PMID 38534790, 2024). "The tumor-suppressing effects from the UCA1 inhibition and its association with the METTL14-miR-375-SOX12 axis were evident in vivo, as well." (PMID 38534790, 2024). "Lnc UCA1: Long non-coding RNA urothelial carcinoma-associated 1 (UCA1) was found to be highly expressed in various cancers, stimulating the proliferation, migration and epithelial–mesenchymal transformation of tumor cells." (PMID 37762249, 2023). "Another study demonstrated that there was a significant association between UCA1 expression and tumour stage, lymphatic metastasis status and patient survival in CRC." (PMID 34976187, 2022). "The lncRNA UCA1 (Urothelial Cancer Associated 1) expression in LSCC patients is significantly higher in tumor tissues compared with adjacent healthy tissues and its serum levels is increased in these patients compared to healthy controls." (PMID 34576322, 2021). "The presence of UCA1 in body fluid was associated with tumor characteristics and patients’ prognosis." (PMID 33477833, 2021). "In short, these findings revealed the association of lncRNA UCA1 in tumor progression, invasion, and metastasis of hepatobiliary cancer by regulating downstream molecules or be regulated by upstream mediators." (PMID 33936199, 2021). "Exosomal lnc-UCA1 levels were greatly increased in PC patient serum and were associated with tumor size, lymphatic invasion, late tumor node and metastasis stage, and poor OS." (PMID 34966744, 2021). "High UCA1 expression predicted a poor prognosis and was associated with distant metastasis and high tumor grade in patients with LUAD." (PMID 34544452, 2021). "A meta-analysis of seven studies validated the result, showing the association of UCA1 expression with tumor size, metastasis, and overall survival." (PMID 33477833, 2021). "Several studies have shown that lncRNA UCA1 plays an essential role in the growth, differentiation, and metastasis of various tumor cells and is associated with chemoresistance in many tumors." (PMID 34777462, 2021). "The lncRNA urothelial cancer‐associated 1 (UCA1) is significantly upregulated in RCCs and is positively correlated with tumor differentiation and tumor node metastasis (TNM) staging." (PMID 34432955, 2021). "In summary, we established a diagnostic panel consisting of serum lncRNA linc00152, UCA1, and tumor marker AFP with superior sensitivity and specificity to diagnose HCC." (PMID 32733618, 2020). "Another important member of lncRNA family, urothelial carcinoma associated 1 (lncRNA UCA1) has been shown to be correlated with tumor growth, progression and recurrence." (PMID 31293964, 2019). "In particular, UCA1 encodes an oncogenic lncRNA shown to disrupt multiple tumour suppressive mechanisms." (PMID 31061680, 2019).
tumor (continued). "Long non-coding RNA Urothelial cancer associated 1 (UCA1) has recently been reported to participate in multiple tumor progression." (PMID 30948929, 2019). "Urothelial Cancer-Associated 1 (UCA1) is one of the lncRNAs mostly associated with tumour progression, metastasis and chemo-resistance in several cancer types." (PMID 30037059, 2018). "Down-regulated NKILA or highly expressed MALAT1 and UCA1 are associated with tumor metastasis, especially lymph node metastasis." (PMID 29416703, 2018). "In HCC patients, elevated serum UCA1 levels were associated with high tumor grade, large tumor size, positive vascular invasion, and advanced TNM stage." (PMID 30159431, 2017). "The lncRNA urothelial carcinoma-associated 1 (UCA1) is significantly overexpressed in most tumor tissues and cancer cells." (PMID 27888635, 2017). "Statistical analysis in clinical and pathologic characteristics suggested that the high expression level of UCA1 was significantly associated with GBC patients’ tumor size, lymph node metastasis, TNM stage and overall survival." (PMID 28624787, 2017). "Then, we investigated the association of UCA1 expression with clinical characteristics: overexpression of UCA1 indicated higher tumor stage and lymph node metastasis in GC patients." (PMID 28569779, 2017). "In our ceRNA network, lncRNA UCA1 was reported to be an independent prognostic factor associated with tumor differentiation and location." (PMID 28536623, 2016). "Urothelial carcinoma-associated 1 (UCA1), an oncofetal gene involved in embryonic development and carcinogenesis, often exhibits extraordinarily high expression in tumor tissues and cancer cells." (PMID 27686732, 2016). "The pooled OR with 95% CI indicated that digestive system malignancy patients with high UCA1 level in tumor tissues were more susceptible to developing LNM (OR = 1.85, 95% CI: 1.28–2.67, P = 0.001)." (PMID 28074092, 2016). "Increased expression of UCA1 has been associated with tumour proliferation, migration and invasion, though the exact mechanisms are yet to be elucidated." (PMID 26191476, 2015). "Furthermore, high UCA1 expression levels are associated with tumor size, invasion depth, metastasis to lymphoid nodules, and TNM stage." (PMID 40277941, 2025). "Additionally, high expression of lncRNA UCA1 in OC cells and tissues was significantly linked to lymphatic metastasis of the tumor." (PMID 38725621, 2024). "OCSC-derived exosomes polarize tumor-associated macrophages (TAMs) into M2 macrophages by transferring UCA1, which targets the LAMC2-PI3K/AKT signaling pathway, further suppressing anti-tumor immunity including CD4+ T cell activation and interferon-γ production." (PMID 39200273, 2024). "UCA1 (Urothelial Carcinoma Associated 1), a lncRNA aberrantly expressed in a spectrum of cancers, is intricately associated with the proliferative, invasive, metastatic, and metabolic attributes of tumor cells." (PMID 39286016, 2024). "Therefore, UCA1 expression is associated with the grade and stage of tumours and the resistance of tumour cells to chemotherapeutic agents." (PMID 38203731, 2023). "Meanwhile, CRC tumor size is reduced when UCA1 is deficient." (PMID 36699052, 2022). "The results suggest that expression of ALKBH5, IGF2BP2, METTL16, AL513165.1, and AP005233.2 is significantly associated with tumor stage and that expression of UCA1, IGF2BP2, METTL16, AL513165.1, AP005233.2, and AC099850.3 is significantly associated with tumor grade." (PMID 34233576, 2021). "In addition, tumor size, metastasis, and recurrence are associated with UCA1 upregulation in GC patients." (PMID 34238213, 2021). "Additionally, hypoxic tumor-derived exosomal lncRNA urothelial cancer-associated 1 (UCA1) was shown to promote angiogenesis via miRNA-96-5p/AMOTL2 (angiomotin-like 2) in PaCa." (PMID 34243775, 2021).